UBE2N (ubiquitin conjugating enzyme E2 N)
Diseases named in the same sentence as UBE2N in open-access papers (continued):
Sharing a sentence is not in itself a finding about the gene and the disease.
tumor (32 papers, 2008 to 2025). "Our findings demonstrate that UBE2N represents a robust biomarker with significant associations with patient prognosis, disease progression, tumor microenvironment characteristics, and treatment sensitivity in LUAD." (PMID 40861472, 2025). "The role of UBE2N in predicting tumor therapeutic susceptibility was characterized using bioinformatics algorithms combined with publicly available CRISPR screening datasets and immunotherapy cohorts." (PMID 40861472, 2025). "The enrichment of genes associated with UBE2N expression in pathways related to metabolism and DNA repair provides a plausible mechanism for its role in promoting tumor proliferation and progression." (PMID 40861472, 2025). "Consistently, the high-UBE2N group displayed markedly higher tumor purity, further supporting the association between UBE2N expression, tumor progression, and immune suppression." (PMID 40861472, 2025). "The mechanism underlying selective elimination of tumor cells with compromised UBE2N- and RNF168-mediated ubiquitination, upon exposure to G4 ligands, was further characterized." (PMID 33963218, 2021). "Irrespective of its binding partner, a low cytoplasmic level of UBE2N could be explained by the consequence of genomic instability (as a repair mechanism) and/or by the cause of the tumor to activate the NF-κB-associated progression of cancer." (PMID 31319803, 2019). "To analyze the molecular mechanism by which UBE2N promotes tumor progression, we screened its co-expressed genes and UBE2N-related DEGs." (PMID 40861472, 2025). "Through comprehensive multi-cohort screening, we discovered that UBE2N acts as an oncogenic driver, accelerating disease progression, remodeling the tumor immune microenvironment, and conferring resistance to both immunotherapy and chemotherapy in LUAD." (PMID 40861472, 2025). "The contrasting enrichment patterns of pathways between high and low UBE2N expression tumors offer intriguing insights into the possible mechanisms by which UBE2N regulates tumor progression and immune response." (PMID 40861472, 2025). "UBE2N protein expression was elevated remarkably in tumor specimens when compared to normal tissues." (PMID 38715121, 2024). "The role of the knockdown of UBE2N in tumor growth was determined in a mouse-bearing xenograft model with injection of 22RV1 cells expressing shUBE2N-1 or shNC." (PMID 38715121, 2024). "As the analysis in TCGA-PRAD data, UBE2N mRNA expression was elevated remarkably in tumor specimens when compared to normal tissues." (PMID 38715121, 2024). "Xenograft model experiment indicated that UBE2N depletion drastically reduced tumor growth, tumor size, and tumor weight." (PMID 36964266, 2023). "These miRNAs target ubiquitin conjugating enzyme E2 N (UBE2N) gene, suppressing the proliferation, migration, and invasion of tumor cells in bone." (PMID 34616676, 2021). "Moreover, UBE2N encodes a protein that is a member of the E2 ubiquitin–conjugating enzyme family and helps to catalyze the synthesis of non-canonical “Lys-63”-linked polyubiquitin chains leading to transcriptional activation of genes involved in tumor proliferation and metastasis." (PMID 32346383, 2020). "Restoring UBE2N expression level in tumor cells leads to inhibition of cell proliferation, which mimics the effect upon miR-147b knockdown in the same cells." (PMID 29371970, 2017). "Here we report that the aberrantly upregulation of miR-147b in HCC tumor samples, further functional study demonstrates miR-147b promote HCC tumor growth by targeting ubiquitin-conjugating enzyme E2N (UBE2N)." (PMID 29371970, 2017). "As miR-147b was upregulated in HCC tumor samples, we further tested UBE2N expression levels in HCC tumor tissues, relative adjacent tissues and normal livers." (PMID 29371970, 2017).
tumor (continued). "More interestingly, the function of UBE2N in HCC tumorigenesis was undefined, and here we found that overexpression of UBE2N significantly represses HCC tumor cells proliferation both in HepG2/Huh 7 cells." (PMID 29371970, 2017). "We further detected UBE2N expression level in HCC tumor cells or normal L02 cell, the data showed that UBE2N was also down-regulated in both HepG2 and Huh 7, compared to the L02 cell line." (PMID 29371970, 2017). "The results showed that the mRNA level of UBE2N was decreased significantly in the tumor tissues compared to that of the adjacent or health tissues." (PMID 29371970, 2017). "As ubiquitinated proteins will be degradated by cells, so the inhibition of UBE2N in tumor cell will lead to tumorigenesis is reasonable." (PMID 29371970, 2017). "The in vitro CRISPR screen showed that UBE2N knockdown promoted T cell-mediated tumor killing." (PMID 40861472, 2025). "UBE2N was also identified as a potential tumor immune evasion promoter in an in vivo CRISPR screen." (PMID 40861472, 2025). "Elevated UBE2N levels in LUAD might promote tumor proliferation and suppress anti-tumor immune response." (PMID 40861472, 2025). "Apart from the association between UBE2N and TME (Tumor microenvironment) remodeling, we further hypothesized that UBE2N may regulate immune effector functions." (PMID 40861472, 2025). "In this study, we observed that UBE2N exerted an active effect on cell viability and tumor growth." (PMID 38715121, 2024). "Assuming that aneuploidy and tissue differentiation lead to increased tumor heterogeneity, UBE2N might be a mere reflection of a possibly decreased therapy response." (PMID 31319803, 2019). "Besides, TRAF6 and Ube2N protein levels were notably lower in tumor cell lines than in PHK confirming the results from gene expression analysis for HPV positive cell lines." (PMID 29472602, 2018). "In addition, UBE2N expression levels progressively decreased with advancing histologic grade in the GSE48465 cohort, highlighting its potential inverse association with tumor differentiation status." (PMID 40861472, 2025). "Tissue microarrays confirmed UBE2N overexpression in LUAD, correlating with tumor size, while UBE2N knockdown suppressed tumor cell viability and induced apoptosis." (PMID 40861472, 2025). "To further confirm these results, we injected A549 cells stably expressing control shRNA, UBE2N shRNA into BALB/c nude mice, and monitored tumor growth in vivo." (PMID 36964266, 2023). "CHD4, like UBE2N, is also involved in several cancer types and has been reported as essential for the maintenance of AML, and required for tumour cell survival in adult HGG." (PMID 37161535, 2023). "The tumour specificity of the gene knockout was tested in neural foetal stem cells (NSC), and our results show that the genes UBE2N, CHD4, LSM11, EED, KANSL1 and KANSL3 are essential for CSC growth and suggest them as therapeutic candidates in paediatric HGG." (PMID 37161535, 2023). "After reviewing the literature, we found that four upregulated genes comprising of TUBA1C, ABCE1, UBE2N, and NIFK had been reported to function in tumor growth, proliferation, migration, metastasis, and prognosis." (PMID 31867042, 2019). "A total of 12 upregulated and one downregulated genes were found to overlap with prognostic and fitness genes, in which four upregulated genes (TUBA1C, ABCE1, UBE2N, and NIFK) had been reported to play roles in tumor growth, cell cycle, migration, metastasis, and prognosis." (PMID 31867042, 2019). "However, the links between tumor microenvironment, immune evasion and UBE2N-mediated tumor progression have not yet been adequately revealed." (PMID 40861472, 2025). "Consequently, BALB/c nude mice were subcutaneously injected with SP1-depleted cells with or without exogenous overexpression of UBE2N and then monitored tumor growth in vivo." (PMID 36964266, 2023).
tumor (continued). "As indicated by UALCAN database, the mRNA expression levels of HLA-A, TMEM129, UBE2D1, UBE2N, UBE2T in BCa tissue were significantly increased compared with that in normal tissue; however, the mRNA expression level of USP5 was similar between normal and tumor tissue." (PMID 34776794, 2021).
cancer (31 papers, 2010 to 2025). A tumor composed of atypical neoplastic, often pleomorphic cells that invade other tissues. "Overexpression of UBE2N has been associated with poor prognosis, chemotherapy resistance, and enhanced NF-κB signaling in various cancers." (PMID 40429973, 2025). "Prior studies have primarily linked UBE2N to the regulation of immune and inflammatory signaling, making its widespread impact on multiple cancer-related pathways unexpected." (PMID 40371639, 2025). "In previous studies associated with cancer progression, UBE2N mostly functioned on the activation/inactivation of cancer-related signaling pathways (e.g., MEK/FRA1/SOX10 and TAK1-p38 MAP kinase cascade)." (PMID 38715121, 2024). "UBE2N’s involvement in DNA damage response and K63-linked ubiquitination is crucial for DNA repair protein recruitment, and its low expression or overexpression is associated with chemotherapy resistance and poor outcomes in some cancers." (PMID 40429973, 2025). "The results showed that except for BIRC3 and UBE2N, other hub UBRs were dysregulated, and most of them were overexpressed in cancer patients." (PMID 40650277, 2025). "In summary, this work presented UBE2N as a novel prognostic biomarker of LUAD, with its expression levels significantly associated with patient survival, disease progression, hallmark cancer pathways, TME characteristics, and therapeutic response." (PMID 40861472, 2025). "Given the important role of UBE2N in mediating cancer progression and TME, we further integrated CRISPR screening, patient cohorts, and immune function algorithms to investigate the association between UBE2N and cancer immunotherapy responsiveness." (PMID 40861472, 2025). "Kaplan-Meier survival analysis across multiple cohorts demonstrated that cancer patients with low-UBE2N expression exhibited significantly prolonged survival compared to those with high-UBE2N expression when receiving immunotherapy." (PMID 40861472, 2025). "UBE2N was a potential promoter of immune evasion and drug resistance, with its high expression suggestive of low responsiveness to cancer immunotherapy and targeted therapies." (PMID 40861472, 2025). "Proteomic analyses and a whole-genome CRISPR-activation screen in pharmacologically and genetically UBE2N-inhibited AML cells unveiled a network of UBE2N-regulated proteins, many of which are implicated in cancer." (PMID 40371639, 2025). "UBE2NL, a ubiquitin-conjugating enzyme-like protein, is structurally related to UBE2N, a protein involved in DNA repair, inflammatory signaling, and cancer progression." (PMID 40429973, 2025). "Across human cancers, the dependency of UBE2N in AML is among the highest, but other cancers also show a UBE2N dependency." (PMID 40371639, 2025). "And UBE2N (also known as UBC13), another member of the E2 enzyme family, was characterized as a potential cancer target in the present study." (PMID 40861472, 2025). "This analysis revealed that UBE2N inhibition can be rescued by reactivation of cancer-related signaling programs." (PMID 40371639, 2025). "Previous studies have considered UBE2N as a promising treatment target for intervention in cell viability in some kinds of cancers." (PMID 38715121, 2024). "Here, our study provided further insight into the complex regulation of UBE2N expression in cancer progression by demonstrating that transcription factor SP1 promotes UBE2N expression at the transcriptional level via binding to the promoter of UBE2N." (PMID 36964266, 2023). "Ubiquitin-conjugating enzyme 2 N (UBE2N) has been demonstrated to play key roles in the progression of various cancers." (PMID 36964266, 2023). "Although UBE2N is overexpressed in many types of cancer, little is known about the mechanisms responsible for that overexpression." (PMID 36964266, 2023). "Among these genes, we focused our attention on UBE2N due to its significant association with ALDOC and its known involvement in the development of various human cancers." (PMID 37724906, 2023).
cancer (continued). "As a member of the E2-conjugating enzyme family, UBE2N, commonly known as UBC13, has been demonstrated to play key roles in the progression of various cancers." (PMID 36964266, 2023). "Ube2v1 complexes with Ube2n and activates the nuclear factor κB (NF-κB) signaling pathway, which is involved in the regulation of cancer." (PMID 37954522, 2023). "We further demonstrated that the ubiquitination pathway was activated on cellular treatment with G4 stabilizers and that CX-5461, in combination with a UBE2N inhibitor, increased cancer cell toxicity." (PMID 33963218, 2021). "Next, we characterized the dose kinetics of CX-5461, PDS and BMH-21 in human cancer cell lines upon UBE2N depletion using WST-1 cell proliferation assay." (PMID 33963218, 2021). "Pan-cancer expression analyses also showed that UBE2N expression was upregulated in most cancers." (PMID 40861472, 2025). "Therefore, UBE2N regulates the ubiquitination and protein expression of a network of cancer-related targets in AML." (PMID 40371639, 2025). "Collectively, these cross-cancer comparisons reveal that role of UBE2N in promoting malignancy might be conserved, but the signaling pathways, cancer hallmarks, and TME interactions it modulates are microenvironmentally and biologically adapted." (PMID 40861472, 2025). "However, little information has been recorded about the targets of UBE2N ubiquitination modification in cancer cells." (PMID 38715121, 2024). "Proteomics and IHC analysis on cancer tissue specimens revealed abnormal UBE2N protein expression." (PMID 38715121, 2024). "Interestingly, recent studies have focused on the functional significance of UBE2N in human cancers." (PMID 37724906, 2023). "However, little is understood about the mechanisms by which UBE2N acts on cancer cell viability." (PMID 38715121, 2024). "Additionally, the molecular mechanisms underlying how UBE2N affects cancer hallmarks and TME remodeling require further exploration in future studies, and advanced techniques such as proteomics and functional genomics could be employed better to understand the specific functions of UBE2N in cancer." (PMID 40861472, 2025). "First, the present study merely focuses on the role of UBE2N in LUAD, while its role in LUSC and other cancer types remains unaddressed." (PMID 40861472, 2025). "UBE2N, along with RNF168, is involved in DNA damage response-related ubiquitin signaling, and this pathway is frequently altered in cancers." (PMID 33963218, 2021). "We have identified a panel of six proteins viz., GOT1, HNRNPA2B1, MAPK1, PAK2, UBE2N, and YWHAB, which contribute to cancer development, and the transition of PCa from androgen dependent to independent stages." (PMID 32322560, 2020). "Moreover, inhibiting UBE2N’s catalytic activity suppressed leukemic stem and progenitor cell functions by destabilizing these critical proteins in AML, which represents a potential therapeutic strategy for immunoproteasome-dependent cancers." (PMID 40371639, 2025).
infection (16 papers, 2013 to 2025). The state of being infected such as from the introduction of a foreign agent such as serum, vaccine, antigenic substance or organism. "This modification blocks UBE2N activity and inhibits acute inflammatory response in the initial stage of infection." (PMID 29752379, 2018). "Depletion of UBE2D1-4, UBE2E1-3 and UBE2N significantly increased the number of PML-positive cells post-infection, in an ICP0-dependent manner, indicating that ICP0 can use multiple E2s to degrade PML." (PMID 23950709, 2013). "In the initial stages of infection, MavC ubiquitinates Ube2N and dampens NF-κB signaling." (PMID 34695417, 2021). "The ubiquitin-conjugating enzyme E2 N (UBE2N or Ubc13) is a member of the family of ubiquitin-conjugating enzymes E2, which mediates the synthesis of polyubiquitin chains linked to lysine 63 and also had its expression increased with infection and treatment in this study." (PMID 36992406, 2023). "However, the regular catalytic activity of Ube2N leading to NF-κB activation is beneficial to long-term intracellular growth of L. pneumophila even though its inhibition is necessary for blocking immune response in the early phase of infection." (PMID 34695417, 2021). "This work presents the structure of MavC–UBE2N–Ub ternary complex and sheds light on the molecular basis for MavC‐induced transglutamination and its mechanistic differences with its homolog MvcA, which counteracts MavC activity by deubiquitinating modified UBE2N in later phases of infection." (PMID 32596129, 2020). "Thus, UBE2N might be a key host factor targeted by different pathogens during infection, albeit by different mechanisms." (PMID 29752379, 2018). "Further IFN and antiviral related proteins were upregulated upon infection with PeV-A3 (EIF2AK2, STAT1), or PeV-A1 (NCAM1, POM121), and downregulated upon PeV-A1 infection (EIF4G1, UBE2N, RANBP2, FLNA)." (PMID 38514653, 2024). "At 24 h after infection, the following genes were upregulated in infected macrophages transfected with the let-7e inhibitor compared to macrophages transfected with NC: Tlr7, Ly96/MD-2, Casp8, Map3k1, Mapk8, Ptgs2/Cox2, Csf 3/GCSF, and the ubiquitin-conjugating enzyme E2N (Ube2n)." (PMID 30555476, 2018).
UBE2N also shares sentences with these, for which no sentence is quoted: bacterial infection (4 papers); lymphoma (4); B cell lymphoma (3); lung adenocarcinoma (3); Parkinson disease (3); colon cancer (2); hepatocellular carcinoma (2); Insulin resistance (2); liver cancer (2); neurodegenerative disease (2); non-small cell lung carcinoma (2); triple-negative breast carcinoma (2); Angelman syndrome (1); autism (1); autoimmune disease (1); bladder cancer (1); breast tumor (1); COVID-19 (1); endometrial cancer (1); eosinophilia (1); familial hypercholesterolemia (1); gastric cancer (1); hematological malignancies (1); Hepatic steatosis (1); Huntington disease (1); immunodeficiency and (1); mastocytosis (1); metabolic disease (1); myocardial infarction (1); nasopharyngeal carcinoma (1).
A further 14 diseases each share a sentence with UBE2N in 1 paper.